IL10 (interleukin 10)
Diseases named in the same sentence as IL10 in open-access papers (continued):
Sharing a sentence is not in itself a finding about the gene and the disease.
tumor (continued). "Analysis of expression of IL-12 and IL-10 suggested that the PBMCs switched their phenotype to anti-tumor phenotype with increased levels of interleukin-12 (IL-12) and decreased IL-10 levels." (PMID 31479484, 2019). "Resveratrol showed anti-tumor and anti-metastatic effects by suppressing the expression of IL-10 and MCP-1 through downregulation of STAT3 signaling pathways." (PMID 30791624, 2019). "Upon PD-1 activation, these cells produced large amounts of IL-10 that potently suppressed tumor-specific T-cell immunity, although the role of HCC-exosomes in this process needs clarification." (PMID 31181729, 2019). "Kwak and colleagues also observed enhanced IL-10 expression in CD4+ and CD8+ T lymphocytes in lungs of tumor-bearing C3-deficient mice." (PMID 31379815, 2019). "TRAPs-elicited CD4+ T cells (TTRAP) directly inhibit the anti-tumor IFN-γ response of CD4+ T and CD8+ T cells and also induce IL-10+ Bregs, which creates a favorable environment to facilitate tumor growth and metastasis." (PMID 31300052, 2019). "In fact, NT cells treated with IL-10 produced tumor activator factors such as RhoA, the glia maturation factor beta, galectin-1, the isocitrate dehydrogenase subunit alpha, and the D-3-phosphoglycerate dehydrogenase." (PMID 31766635, 2019). "Enhanced production of PGE2, IL-1β, IL-6, TGF-β as well as arginase, indoleamine 2,3-dioxygenase (IDO) and IL-10 from MDSCs implicitly mediate reciprocal differentiation of Th17 and Treg cells in a defined circumstance of tumor microenvironment." (PMID 31024835, 2019). "In particular, T cells in the tumor proximity (peritoneum) presented higher perforin, granzyme B, lower IL-10 and a more beneficial mRNA profile, compared to classical GM4-1 step vaccination." (PMID 30621204, 2019). "Simultaneous blockade of PD-1 and IL-10 results in increased survival and delays tumor growth in ovarian cancer, leading to an enhanced antitumor immune response and reduced infiltration of immunosuppressive MDSCs." (PMID 31379886, 2019). "In a positive feedback loop, STAT3 subsequently transduces signals for all members of the IL-6 and IL-10 families, which leads to chronic amplification of pathways that support tumor growth." (PMID 31842362, 2019). "IL-10 suppresses anti-tumor immune response by modifying macrophages to release tumor promoting factors." (PMID 31479484, 2019). "Blocking cytokine interleukin 10 (IL-10) at the time of immunisation enhances vaccine induced T cell responses and improves control of tumour cell growth in vivo." (PMID 30897137, 2019). "As an example, the presence of TNF, IL-1, IFN-γ and hypoxic conditions in the TME induces the secretion of proangiogenic and immune suppressive factors (including EGF, PDGF, fibroblast growth factor 2, FGF-2, VEGF, IL-6 and IL-10) allowing tumor proliferation." (PMID 30781344, 2019). "Using biopsies from patients with oral squamous cell carcinoma, tumor-associated macrophages (TAMs) expressing CD163+CD204+ promoted T cell apoptosis and immunosuppression via IL-10 and PD-L1 production, thus predicting an unfavorable prognosis." (PMID 32039024, 2019). "For example, the induction of interleukin (IL)-6, IL-10, and CSF-1 contributes to the proliferation and invasion of tumor cells, whereas the secretion of pro-inflammatory IL-1β enhances the antitumor immune response." (PMID 31455032, 2019). "TAMs have a stark different function compared to macrophages derived from healthy or inflamed tissues, possibly because of their exposure to tumor-derived molecules, such as IL-4, IL-10, and TGF-β." (PMID 31001266, 2019). "In a spontaneously metastatic 4T1 mammary carcinoma mouse model, the increase in myeloid-derived suppressor cells (MDSCs) production of IL-10 decreased the macrophage production of IL-12, and thereby impaired tumor immunity." (PMID 32039024, 2019).
tumor (continued). "Based on our previous report, elevated anti-inflammatory cytokines such as IL-6, IL-10, and TGF-β in tumor-associated ascites are related to tumor progression." (PMID 31753019, 2019). "For example, tumor-derived cytokines, including IL-6 and IL-1β, as well as cytokines released from activated T cells, such as IL-4 and IL-10, develop common myeloid progenitor cells into MDSCs." (PMID 31048856, 2019). "IL-10 is associated with a deficient anti-tumor immune response, increased TGF-β levels and feed-forward STAT3 signaling in tumor cells, microglia and probably astrocytes." (PMID 31186414, 2019). "The high levels of IFN-γ, low levels of IL-10, and high ratio of IFN-γ/IL-10 revealed a Th1 shift in the tumor microenvironment in the MBT-treated tumors." (PMID 31083581, 2019). "Autocrine complement C3 inhibits IL-10-mediated cytotoxic properties of tumor-infiltrating CD8 T lymphocytes through complement receptors C3aR and C5aR1, and enhances melanoma and breast cancer growth." (PMID 31001273, 2019). "Purified PDATME DC produced markedly elevated TNFα, IL-6, and IL-10 in culture compared with splenic DC from tumor-bearing hosts." (PMID 30926808, 2019). "SW480- and U87-MG-derived exosomes induce the release of IL-1α, IL-8 and MCP-1 by monocytes, while exosomes released from all tumor cell lines after LPS treatment trigger the production of IL1β, IL-10, IL-6, MIP-1α, MIP-1β and TNF-α cytokines." (PMID 31186484, 2019). "On the one hand, IL-10 can inhibit NF-κB signaling, exerting an anti-tumour effect, but, on the other, because of its immunosuppressive effect, it can allow cell maturation and differentiation, thus fostering cancer immune-evasion." (PMID 30764482, 2019). "Systemic IgE treatment in this model was also associated with a specific cytokine signature, featuring elevated levels of TNFα, MCP-1 and IL-10 in the tumour microenvironment and upregulated expression of TNFα by tumour-associated macrophages in rat lungs." (PMID 30956175, 2019). "We further studied the changes of Breg cells and the IL-10 level before and after the surgery and found that they were significantly decreased after the tumor resection." (PMID 31316301, 2019). "Conversely, the inability of hematopoietic cells to respond to CXCL9/10 resulted in decreased tumor infiltration by CTLs and Tregs, decreased levels of IL-10 and TGF-β, and increased numbers of tumor lesions." (PMID 31775909, 2019). "TAMs promote tumor progression via stimulation of cancer cell proliferation, as well as through secretion of IL-10 and TGF-β which impair effector T cells and inhibit DC maturation." (PMID 31921140, 2019). "Immunohistochemistry analysis showed that IL-10 protein expression in HCC tissues was higher than that in tumor-adjacent tissues." (PMID 31142329, 2019). "RT‐PCR showed that in comparison to those from the shMACC1‐NC and shMACC1 groups, the expression of IFN‐γ and IL‐2 was increased and the expression of IL‐10 was decreased in tumor samples from the shMACC1 group." (PMID 31557409, 2019). "It has been established that T cells express C3a and C5a receptors, which when bound by ligand result in IL-10 production and suppression of tumor-specific CD8+ T cell mediated cytotoxicity in melanoma." (PMID 31164885, 2019). "Activation of S1PR4 primed apoptotic tumor cell-stimulated macrophages for signaling via the nerve growth factor receptor TrKA, which induced among others IL-6 and IL-10 expression." (PMID 31379883, 2019). "TAMS (as identified by CD68 antibodies) are thought to be driven by immunosuppressive cytokines such as IL-10 and TGF-beta and have been associated with suppressing T cell tumor response and promoting tumor growth and spread." (PMID 31903172, 2019). "These included LPS/IL-1 mediated inhibition of RXR function, TNFR2 signaling, metastasis signaling, and tumor-promoting inflammation signaling such as that mediated by IL-10, IL-6, and NF-κB (all P < 0.001)." (PMID 31001473, 2019).
tumor (continued). "In a murine breast cancer model, TAMs were the primary source of IL-10 and IL-10R was expressed at high levels on DCs leading to the suppression of the anti-tumor cytokine IL-12." (PMID 31921140, 2019). "A more recent study identified the CD11b+CD11c+ MDSC as an important IL-10-producer in tumor microenvironments which helps to establish a friendly environment for tumor growth." (PMID 31552179, 2019). "The local IL‐10 from tumour cells or macrophages maintains immune suppression 13, and VEGF produced by macrophages 47 promotes angiogenesis in the microenvironment." (PMID 31418859, 2019). "The high ratio of IFN-γ and IL-10 in the MBT-treated tumors indicates that the Th1 polarization of the tumor environment." (PMID 31083581, 2019). "Whereas, IL-10 and IL-22 promote tumor cell survival, proliferation and angiogenesis via signal transducer and activator of transcription (STAT) 1,3,5 signalling pathways." (PMID 31340751, 2019). "Inhibition of p38 restored the IL-12:IL-10 balance in Dex or tumor lysate-conditioned healthy cDC2 and enhanced T-cell proliferation and interferon-gamma (IFNγ) production." (PMID 31143512, 2019). "M2 type macrophages activate secretion of interleukin 6 (IL-6), TGF-β and interleukin 10 (IL-10), and VEGF to enhance tumor growth which are associated with a worse prognosis." (PMID 31579438, 2019). "A recent study showed delayed tumor growth, decreased production of IL-10, IL-2, and TGF-β, and increased survival of mice after inoculation of the FOXP3-silenced B16F10 melanoma cell line compared to mice injected with the wild-type cell line." (PMID 31547627, 2019). "The same group also identified macrophages as a primary source of IL-10 and that inhibition of IL-10 receptor induced reduction of the breast cancer tumour burden if combined with chemotherapy, with an equivalent effect caused by blockade of CSF-1R." (PMID 31331034, 2019). "In cancer, however, IC have been shown to be tumor-promoting, by stimulating macrophage IL-10 secretion and potentiating an immunosuppressive microenvironment." (PMID 30972056, 2019). "TAMs are typically polarized in the pro-tumor ‘M2′ subtype which secrete high levels of IL-10 and TNFα, and decreased IL-12 to promote the immunosuppressive environment and increase invasiveness in cancer cells." (PMID 31443240, 2019). "We also detected the increased proportion of MDSC subgroups with high expressions of membrane-bound TGF-beta 1, VEGF, and IL-10, both in residual tumor tissues and in lung metastases after operations." (PMID 31552179, 2019). "TGFβ, IL-4, and IL-10 are anti-inflammatory pleiotropic signaling molecules that are involved in critical functions during tumor promotion and progression." (PMID 31174326, 2019). "Production of TGFβ, VEGF, PGE2, and IL-10 by tumor endothelial cells can also act directly on T cells to suppress their function." (PMID 31998326, 2019). "In contrast, M2 TAMs are activated by the Th2 cytokines like IL-4 and IL-10 and responsible to the expression of IL-10 and arginase, immunosuppression, as well as the promotion of tumor growth." (PMID 31781219, 2019). "Other studies examining IL-4′s role in prostate cancer suggest that serum IL-4 concentrations are elevated in patients with benign prostatic disease, and IL-10 and IL-4′s pro tumor effects likely reflect their immunosuppressive properties." (PMID 31174326, 2019). "The activated FcγRII low/− B cells from the HCC tumor subsequently suppress autologous tumor-specific cytotoxic T cell immunity through IL-10." (PMID 31540435, 2019). "Recent studies suggest that a new mechanism plays an important role in complement signaling-mediated suppression of antitumor immunity: direct inhibition of IL-10 production in CD8+ tumor infiltrating lymphocytes (TILs) in TME." (PMID 31379815, 2019). "IL-10 is an anti-inflammatory cytokine responsible for maintenance of self-tolerance, but also inhibition of the anti-tumor immune response." (PMID 31681327, 2019).
tumor (continued). "As a consequence of the immunosuppressive tumor microenvironment, namely due to high IL-10 and TGF-β levels, TAMs are reported to adopt features common to M2-like macrophages." (PMID 31481956, 2019). "It has been reported that M1 macrophages decrease the viability of A549 cells by inducing apoptosis and senescence, while M2 macrophages secrete IL-10 and drive tumor progression." (PMID 31798581, 2019). "In this context, previously published observations that IL-10 is a tumor growth factor and IFN-γ exerts a cytotoxic effect on metastatic cells seem to be particularly worth emphasizing." (PMID 30770758, 2019). "Comparing the expression pattern with respect to membrane-bound and soluble isoforms of HLA-G in tumor tissue, we found that IL-10 and IFN-γ expressions were higher in membrane-bound isoforms." (PMID 30859089, 2019). "FGF, GM-CSF, IL-6, and IL-10 are growth factors and cytokines well known for playing important roles in promoting tumor progression and/or immune evasion." (PMID 31013891, 2019). "Other studies also reported that co-administration of IL-10-specific siRNA-loaded nano-carriers and a DC vaccine enhanced antitumor immune responses and inhibited tumour growth and metastasis." (PMID 30717461, 2019). "EPHX2 (-/-) /IL10(-/-) double knockout mice also displayed decreased precancerous dysplasia and tumor size, when compared to IL10(-/-) mice." (PMID 31002701, 2019). "TAMs in thyroid tumors display an M2 phenotype (i.e. express CD163 and interleukin 10), and are likely to promote tumor progression and/or inhibit tumor elimination." (PMID 31113465, 2019). "IL-10 in the TME is derived from several components including tumor cells in addition to infiltrating leukocytes including T and B cells, macrophages, and NK cells." (PMID 31681327, 2019). "Once recruited, interleukins such as IL-4, IL-13 and IL-10 produced by tumor infiltrating lymphocytes (TILs) promote differentiation of macrophages towards an M2 phenotype." (PMID 29601534, 2018). "Common indications for the immunosuppressive activity were tumour growth in vivo and interleukin—10 (IL-10) release from human PBMCs in vitro." (PMID 30001404, 2018). "In this study, we demonstrate that TRAPs are a novel mechanism exploited by tumor cells for immune suppression, including inducing M2 polarization as reflected by increased expression of PD-L1 and IL-10." (PMID 30563569, 2018). "Counter-regulatory signals exist that suppress the development of an anti-tumor response, such as IL-10, Treg cells, and PD-L1." (PMID 30400835, 2018). "In line with this evidence, a specific TAM-M2-like cell phenotype secreting high IL-10 and low IL-12 levels suppresses anti-tumor immune response while promoting tissue remodeling and neo-angiogenesis favoring metastatic dissemination." (PMID 29652798, 2018). "The tumour-educated M2-like macrophages resemble trophic/developmental macrophages, downregulate tumouricidal activity and inhibit cytotoxic T cells (CTLs) via IL10 secretion." (PMID 30577495, 2018). "The model results predicted that injecting M1 macrophages or Th1 cells, administering anti-TGF-β to reduce angiogenesis and simultaneously reducing the production of IL-4 and IL-10 is a promising strategy to eliminate a tumor." (PMID 35847834, 2018). "Such exosomes are internalized by neighboring macrophages that, in turn, undergo reprogramming and produce anti-inflammatory and tumor supportive factors including IL-10, TGF-β, and MMPs." (PMID 29472616, 2018). "The inhibitory effects of IL-10 on tumour progression have previously concentrated on the anti-tumour immune effects; one of the suggested mechanisms is via inducing infiltration and activation of cytotoxic CD8 cells." (PMID 29256156, 2018). "The main objective of our work was to improve the antitumor effect of DCs stimulated with tumor antigens by diminishing the IL-10 production in TME." (PMID 29954431, 2018).
tumor (continued). "The metastatic subline HT-L1 expressed higher levels of IL-6 and IL-10 than the primary tumor subline HT-S1." (PMID 30209389, 2018). "Regulatory B-cells are expected to promote tumor growth by suppressing immune response through IL-10 and STAT3." (PMID 30383866, 2018). "CXCR4 expressing plasmacytoid DC (pDC) precursor cells are recruited into the ovarian TME by CXCL12 and IL-10 in the tumor." (PMID 30200478, 2018). "Specifically, IL-2/CD40 reduced expression of several regulatory molecules (CD39, A2AR, A2BR, PD-L1, ICOS, and/or IL-10) on young tumor-infiltrating CD11c+ cells and CD4+ T cells, suggesting reduced suppressive activity." (PMID 30560130, 2018). "IL-10 can be secreted by both Th1 and Th2 cells and has a dual role on tumor development and carcinogenesis." (PMID 29721190, 2018). "IL-10 inhibits tumor growth and metastasis in an animal model, and it inhibits tumor metastasis through an NK cell-dependent tumor killing mechanism." (PMID 29467412, 2018). "In this scenario, Treg cells activated by miR-214 produce high levels of IL-10, thereby promoting immunosuppression and facilitating tumor engraftment in mice." (PMID 29652798, 2018). "A study has revealed that IL-13 along with Th2 cytokines such as IL-10 and IL-4 assist in the immunological tumor escape and interfere with the induction of an antitumor response." (PMID 30643796, 2018). "Other studies also showed that cytokine IL-4 and IL-10 expression is reduced and the tumor immune response is decreased by inhibiting the expression of ICOS and its receptor, which is not conducive to activation of T cells." (PMID 29316975, 2018). "Whereas M2 macrophages can be seen as pro-tumorgenic by promoting the metastatic capacity of a tumor due to production of multiple cytokines (e.g., IL-1, IL-6, IL-10, VEGF and TGF-β)." (PMID 29601534, 2018). "For instance, the induction of interleukin-6 (IL-6), IL-10, and colony stimulating factor 1 (CSF-1) contributes to the proliferation and invasion of tumor cells and thereby displays a pro-tumorigenic role." (PMID 30115069, 2018). "Yet, tumour cells and the irradiated tumour microenvironment also produce M2 activators (IL-4, IL-10, IL-13, TGF-β, and PGE2)." (PMID 30178305, 2018). "Both IL-6 and IL-10 showed positive cytoplasmic staining in BC cells with a heterogeneous staining pattern between, as well as within, certain tumour cores varying from weak to intense." (PMID 29256156, 2018). "IL-6 and IL-10 in ascites promote the differentiation of macrophages into the immunosuppressive M2 phenotype, which stimulates tumor cell proliferation and suppresses the effector functions of cytotoxic T cells." (PMID 30687337, 2018). "Tumor cells produce large amounts of IL-10 that contributes to tumor progression; in most types of cancers, serum IL-10 levels correlate with disease severity." (PMID 30154786, 2018). "The tumor's immunosuppressive activities of are generally thought to be conveyed by soluble prostaglandin E2 and cytokines like IL‐10 and TGF‐β1 that bind to receptors on target immune cells." (PMID 29601673, 2018). "In fact, other studies have shown that tumor cells can manipulate the behavior of astrocytes; by releasing a variety of factors, such as IL-10 and interferon beta (IFN-β), can also stimulate the anti-inflammatory phenotype of these cells." (PMID 30123112, 2018). "The model containing a combination of unstimulated leukocyte IL-10 production, heart rate, and gross tumor volume appeared to be the best predictor of inflammation (Adjusted R squared 0.553; Cp 2.405; p < 0.034)." (PMID 29606140, 2018). "Patients with tumor diameter ≥5 cm had significantly higher plasma levels of IL-8 and IL-10 as compared with those with tumor diameter <5 cm (P < .05 for all)." (PMID 29742685, 2018). "Anti-tumour function of dendritic cells is suppressed through IL-1044 and we found IL-10 to be upregulated in Krt76−/− mice, particularly after 4NQO treatment." (PMID 30143634, 2018).